FMO6P (flavin containing dimethylaniline monoxygenase 6, pseudogene)
Description:
Member of the flavin-containing monooxygenase (FMO) family of NADPH-dependent monooxygenases, which catalyze the oxygenation of nucleophilic heteroatom-containing compounds such as xenobiotics and drugs. In humans, FMO6 is unlikely to encode a functional monooxygenase due to defective transcript processing and the presence of truncating variants. No enzymatic activity has been demonstrated for the human protein.
Synonyms: formerly FMO6
Gene: Transcribed unitary pseudogene on chromosome 1 (171,138,212 to 171,161,396, forward strand). Ensembl gene ENSG00000117507.
Subcellular location: Membrane
Diseases named in the same sentence as FMO6P in open-access papers:
FMO6P is named in the same sentence as 2 diseases in open-access papers, as found by Europe PMC text mining. Sharing a sentence is not in itself a finding about the gene and the disease. The quoted sentences say what the papers report.
gastric cancer (1 paper, 2015). A primary or metastatic malignant neoplasm involving the stomach. "However, most of the lncRNAs such as DRD5, FMO6P, SNAR-A3 and TPRXL showed in our microarray haven’t been identified and need further investigation to clarify their roles in gastric cancer." (PMID 25928635, 2015).
nicotine dependence (1 paper, 2017). Physical and psychological dependence on nicotine. "On the other hand, if the signal we identified in FMO6P is not the surrogate for effects of SNPs in FMO3, but has an independent effect on nicotine dependence, then further research will be needed to clarify the underlying function of FMO6P." (PMID 28413702, 2017). "Specifically, we focused on the two genomic segments including FMO1, FMO3 (protein coding genes for FMO 1 and 3), and FMO6P (pseudo gene), and aimed to investigate the potential association between FMO genes and nicotine dependence." (PMID 28413702, 2017). "In summary, we tested the genetic effects of three FMOs genes (FMO1, FMO3, and FMO6P) on nicotine dependence by performing targeted sequencing on 2,852 nicotine‐dependent and nondependent smokers." (PMID 28413702, 2017). "Specifically, we focused on the two genomic segments including FMO1,FMO3, and pseudo gene FMO6P, and aimed to investigate the potential association between FMO genes and nicotine dependence." (PMID 28413702, 2017).